IL31 (interleukin 31)
Diseases named in the same sentence as IL31 in open-access papers (continued):
Sharing a sentence is not in itself a finding about the gene and the disease.
xerosis (2 papers, 2025 to 2026). "In uremic pruritus, it is probably secondary to CKD‐related xerosis, higher skin‐surface pH, and gut microbiota imbalance, with an immune milieu marked by elevated interleukin (IL)‐2, IL‐6, IL‐31, histamine, and altered monocyte subsets." (PMID 40528508, 2025).
acromegaly (1 paper, 2025). Acromegaly is an acquired disorder related to excessive production of growth hormone (GH) and characterized by progressive somatic disfigurement (mainly involving the face and extremities) and systemic manifestations. "In addition, IL31 was also found to be associated with pituitary hyperfunction, acromegaly, and gigantism." (PMID 40906170, 2025).
Anxiety (1 paper, 2021). Intense feelings of nervousness, tension, or panic often arise in response to interpersonal stresses. "IL-33 and IL-31 were significantly higher in patients with AA than in HCs; there were no significative relationship between depression or anxiety with IL-31 or IL-33." (PMID 33810498, 2021).
atopic asthma (1 paper, 2017). An asthma that is characterized by symptoms that are triggered by an allergic reaction caused by inhaled allergens such as dust mite allergen, pet dander, pollen and mold. "A direct correlation between SCF, IL-31 and FEV-1/ FVC %, CRP and wheezing existed and suggested that both SCF and IL-31 play an important role in mediating inflammation and enhancing severity of atopic asthma." (PMID 28100228, 2017).
atrophic gastritis (1 paper, 2020). "In superficial gastritis and atrophic gastritis, the expression levels of chemokines/interleukins are relatively the same (IL14, CXCL14, and CCL28 had higher expression levels; IL3, CCL26, IL31, etc., had lower expression levels), only with a slight difference." (PMID 33426088, 2020).
chronic asthma (1 paper, 2020). An asthma that is characterized by the development of persistent airway inflammation and recurrent attacks of breathlessness and wheezing, which vary in severity and frequency. "Accordingly, we observed increased IL31 levels in the chronic asthma model, which were exaggerated in WNT5A transgenic mice in response to allergen exposure." (PMID 32317758, 2020).
chronic lymphocytic leukemia (1 paper, 2019). "Transcriptomic profiling from chronic lymphocytic leukemia patients successfully treated with CAR-T cells, revealed a general implementation of the IL-6/STAT3 signaling pathways, as indicated by increased production of IL-6, IL-17, IL-22, IL-31 and CCL20." (PMID 30999624, 2019).
dermatitis herpetiformis (1 paper, 2017). "So far there are no data connected with the role of IL-31 in development of itch in a course of autoimmune blistering diseases as well as itch intensity in a course of dermatitis herpetiformis." (PMID 28808661, 2017).
Down syndrome (1 paper, 2014). "In our study, detected levels of IL-31 in the plasma of women with fetal Down syndrome were lower when compared to women with a healthy fetus." (PMID 25477715, 2014). "Patients with fetal Down syndrome had higher plasma concentration of 1 chemokine: CXCL7 (NAP-2) and lower plasma concentration of 4 chemokines, HCC-4, IL-28A, IL-31, and MCP-2, when compared to patients with healthy fetus." (PMID 25477715, 2014).
endometritis (1 paper, 2016). An acute or chronic, usually bacterial infectious process affecting the endometrium. "In addition, we were unable to illustrate the correlation between IL-31/IL-33 and endometritis." (PMID 27340318, 2016).
enthesitis (1 paper, 2018). Inflammation at the site of insertion of ligaments, tendons, and other fibrous structures into bone. "On multivariable analysis, risk of low BMD was increased with each 10-pg/ml increase in IL-31 (OR 1.385 [95% CI 1.051–1.823], p = 0.01), together with male gender, enthesitis and MRI-SI-positivity." (PMID 29769586, 2018).
eosinophilic diseases (1 paper, 2021). "As eosinophils are susceptible to the effects of IL-31, IL-31 can represent an appealing target for the treatment of eosinophilic diseases in cats." (PMID 34357916, 2021).
Erythema (1 paper, 2025). Redness of the skin, caused by hyperemia of the capillaries in the lower layers of the skin. "One study showed upregulation of messenger RNA encoding IL‐31 in the skin of atopic dogs as early as 6 h after allergen challenge, when erythema was not yet evident." (PMID 40042058, 2025).
fibrosis (1 paper, 2021). the formation of excess fibrous connective tissue in an organ or tissue in a reparative or reactive process. "Collectively, both IL-31 and IL-31RA expression was up-regulated in SSc DFs, suggesting a role of the IL-31/IL-31RA axis in SSc fibrosis." (PMID 34642338, 2021).
food allergy (1 paper, 2018). Gastrointestinal disturbances, skin eruptions, or shock due to allergic reactions to allergens in food. "However, it has not been investigated if IL‐31 is involved in food allergy." (PMID 29992767, 2018).
Hyperglycemia (1 paper, 2020). An increased concentration of glucose in the blood. "In our study, hyperglycemia was associated with lipid peroxides formation and secretion of proinflammatory cytokines, particularly IL-6, IL-31 and IL-33." (PMID 32824505, 2020). "Our results confirm IL-31 secretion in the hyperglycemic state and its inhibition after treatment with both doses of Physalis extracts and quercetin, demonstrating thus their beneficial effects on inflammation associated with hyperglycemia." (PMID 32824505, 2020). "Particularly PhyF extract, diminished lipid peroxidation and inhibited the IL-31 and IL-33 secretions induced by hyperglycemia." (PMID 32824505, 2020). "The exposure of HUVECs cells to hyperglycemia induced IL-31 secretion compared to normoglycemia (p < 0.001)." (PMID 32824505, 2020). "The pretreatment of HUVECs exposed to hyperglycemia with two doses of PhyF and quercetin for 24 h significantly diminished the IL-31 secretion (p < 0.001)." (PMID 32824505, 2020). "In our study, the NFkB/pNFkB ratio increased in hyperglycemia compared to normoglycemia, suggesting the activation of the NFkB transcription factor in hyperglycemic conditions, in correlation with the increase of oxidative stress and inflammatory markers, especially IL-6, IL-31 and IL-33." (PMID 32824505, 2020).
Hyperkeratosis (1 paper, 2023). Hyperkeratosis is a histopathological term defining a thickened stratum corneum and may be present in many different skin conditions, with many possible overlaps. "In this study, we show for the first time, that the addition of histamine to disease-associated full-thickness skin models stimulated with TH2 cytokines (IL-4, IL-13, IL-31) results in morphological changes of the epidermal layer, interpreted as hyperkeratosis." (PMID 36615633, 2023).
intervertebral disc disease (1 paper, 2023). "In individual patients, where syringomyelia was accompanied by otitis media and/or interna, or intervertebral disc disease, higher IL-31 levels were measured in serum and CSF." (PMID 37993920, 2023).
keloid (1 paper, 2025). An irregularly shaped, elevated mark on the skin caused by deposits of excessive amounts of collagen during wound healing. "To investigate pruritus mediators in keloids, we analysed the Th2 cytokines, IL-4, IL-13, and IL-31, and SP neuropeptide gene expression in anterior chest keloids, ear keloids, and normal skin using real-time PCR." (PMID 40830367, 2025).
malaria (1 paper, 2024). Malaria is a serious and sometimes fatal disease caused by a parasite that commonly infects a certain type of mosquito which feeds on humans. "It has been observed that clinical or severe malaria is associated with increased levels of pro-inflammatory cytokines, including IL-1β, IL-6, IL-8, IL-10, IL-12, IL-13, IL-31, IL-33, and TNF-α." (PMID 39204168, 2024). "It has been observed that TNF-α, IL-31, and IL-33 are associated with clinical or severe malaria." (PMID 39204168, 2024).
mental disorder (1 paper, 2021). A disease that has its basis in the disruption of mental process. "According to literature, we found 13 research papers that evaluated interleukin 33 or interleukin 31 levels in subjects affected by mental disorders." (PMID 33810498, 2021). "We found 13 research papers that evaluated interleukin 33 or interleukin 31 levels in subjects affected by mental disorders." (PMID 33810498, 2021). "The path to further studies to better define the role of alarmins in mental disorders needs to be built around specific psychiatric variables as age, phase of disease, age from onset, number of acute episodes, comorbidity, drugs used, and immunological variables such as sST2 and IL-31." (PMID 33810498, 2021).
metastatic disease (1 paper, 2020). "MBC patients’ exosomes had a low concentration of MIP-3 alpha, IL-23, M-CSF, Eotaxin-3, BLC, SDF-1 alpha, IL-2R, MDC, FGF-2, IL-22, and IL-31, suggesting that metastatic disease may be associated with immune suppression related to low exosomal cytokines." (PMID 32826923, 2020).
mite infestation (1 paper, 2023). Infestations with arthropods of the subclass acari, superorder Acariformes. "Mite infestation and IL-31 administration increased the LLS counts and upregulated DRG neuronal IL-31RA expression, and the LLS counts showed a close correlation with DRG neuronal IL-31RA expression in the NC/Nga and BALB/c mice." (PMID 36674561, 2023).
myocarditis (1 paper, 2025). Myocarditis is a condition that is characterized by inflammation of the heart muscle (myocardium). "In contrast, higher genetically determined plasma levels of IL31 were positively associated with an increased risk of myocarditis, as well as sensory organ disorders such as vitreous body disorders." (PMID 40906170, 2025). "Similarly, RPIA [OR (95% CI): 0.317 (0.170−0.589), p = 2.84 × 10−4] was also protective, whereas PDIA5 [OR (95% CI): 1.328 (1.130−1.561), p = 5.88 × 10−4] and IL31 [OR (95% CI): 1.906 (1.254−2.896), p = 0.003] were risk factors for myocarditis." (PMID 40906170, 2025).
Nephroblastoma (1 paper, 2014). An embryonal neoplasm characterized by the presence of epithelial, mesenchymal, and blastema components. "In contrast, levels of IL-16; IL-31; insulin receptor (IR); immunoglobulin M (IgM); Karyopherin-a2; nephroblastoma overexpressed (NovH, also known as insulin-like growth factor binding protein 9); SCF sR; TPSB2; VEGF sR2; and sL-Selectin decreased following treatment." (PMID 25100134, 2014).
non-small cell lung carcinoma (1 paper, 2018). A group of at least three distinct histological types of lung cancer, including non-small cell squamous cell carcinoma, adenocarcinoma, and large cell carcinoma. "Sera and bronchoalveolar lavage fluid (BALF) taken prior to chemotherapy from patients diagnosed with non-small cell lung cancer (NSCLC) were analyzed by enzyme linked immunosorbent assay (ELISA) to assess circulating levels of IL-27, IL-29, IL-31, and IL-33." (PMID 30205617, 2018).
ocular sarcoidosis (1 paper, 2022). A leading cause of inflammatory eye disease is sarcoidosis. "A study that compared the vitreous concentrations of inflammatory cytokines between PDR and ocular sarcoidosis reported that IL-4, IL-17A, IL-31, and TNFα were significantly elevated in PDR, indicating the involvement of Th2 and Th17-related immune responses in the pathogenesis of PDR." (PMID 35806888, 2022).
otitis (1 paper, 2023). "In CSF samples the IL-31 content was highest in dogs with concomitant neurological diseases (group A.3) showing itching behaviour followed by dogs with syringomyelia and otitis (group A.2) and itching behaviour." (PMID 37993920, 2023). "In subgroup A.2 with syringomyelia and otitis (group A.2) three dogs (n = 3/5) had higher IL-31 levels in serum than the highest IL-31 level in healthy dogs." (PMID 37993920, 2023). "Indeed, in comparison only a part of dogs with syringomyelia and otitis or concomitant neurological disease and increased itching behaviour had increased IL-31 levels in the present study." (PMID 37993920, 2023). "When comparing the groups, the mean IL-31 content in the serum was higher in dogs with syringomyelia and additional otitis showing itching behaviour (group A.2) in comparison to the other dogs with syringomyelia displaying itching behaviour from group A.1 + A.3." (PMID 37993920, 2023). "In subgroup A.2 with syringomyelia and otitis, the mean IL-31 level in serum tended to be higher compared to subgroups A.1 with syringomyelia only and A.3 with syringomyelia and other neurological diseases, although this difference was not significant (p = .2263)." (PMID 37993920, 2023).
otitis media (1 paper, 2023). Inflammation of the anatomical structures of the middle ear, which is most often caused by an infectious process. "Individual patients with syringomyelia (especially dogs with otitis media or otitis media and interna or intervertebral disc herniation) showed high IL-31 levels in serum and CSF samples, but the difference was not statistically significant." (PMID 37993920, 2023).
Parkinson disease (1 paper, 2025). A progressive degenerative disorder of the central nervous system characterized by loss of dopamine producing neurons in the substantia nigra and the presence of Lewy bodies in the substantia nigra and locus coeruleus. "Novel Win the Skin Immune System Trick (WISIT) vaccines however have been shown to induce substantially stronger Ab responses than CCVs in Parkinson’s Disease, and so may be capable of overcoming IL-31 tolerance to effectively treat CP." (PMID 39932924, 2025).
pertussis (1 paper, 2023). A contagious bacterial respiratory infection caused by Bordetella pertussis. "LASSO modeling also revealed positive association between pertussis IgG levels with CB concentrations of T-cell-derived cytokines IL-2, IL-17A, and IL-31, but in contrast to tetanus, APRIL was negatively associated with pertussis, as was IL-33." (PMID 37251388, 2023). "Using a least absolute shrinkage and selection operator (lasso) regression model, cord blood (CB) plasma IL-2, IL-17A, IL-31, and soluble CD14 (sCD14) were positively associated with pertussis IgG levels at 12 months, while CB plasma concentrations of APRIL and IL-33 were negatively associated." (PMID 37251388, 2023). "In CB samples, plasma IL-2, IL-17A, IL-31, sCD14, and switched memory B cells were positively associated, whereas APRIL, IL-33, non-switched memory B cells, and plasmablasts were negatively associated with 12-month pertussis IgG levels." (PMID 37251388, 2023).
Pleural effusion (1 paper, 2016). The presence of an excessive amount of fluid in the pleural cavity. "Thus, the diagnostic accuracy of the IL-31 levels in pleural effusion was 92.3% (84/91)." (PMID 26864868, 2016). "Thus, we speculated that IL-31 may play a role in the production of pleural effusion." (PMID 26864868, 2016).
pneumonia (1 paper, 2016). An acute, acute and chronic, or chronic inflammation focally or diffusely affecting the lung parenchyma, caused by an infection in one or both of the lungs (by bacteria, viruses, fungi, or mycoplasma.). "The IL-31 levels did not significantly differ among the pneumonia with pleural fluid, active pulmonary tuberculosis (PTB) and healthy control groups." (PMID 26864868, 2016). "Only in the pneumonia with pleural fluid group, the IL-31 levels of the plasma were higher than those in the TPE group (P = 0.047), while the IL-31 levels in this group did not increase by antigen stimulation compared to that without stimulation (P = 0.34) which could be used for differentiation." (PMID 26864868, 2016).
pulmonary arterial hypertension (1 paper, 2016). Pulmonary arterial hypertension (PAH) is a group of diseases characterized by mean pulmonary artery pressure >20 mmHg and elevated pulmonary arterial resistance leading to right heart failure. "In a recent study, the IL-6/IL-31-signaling axis was found to be critical for the pathogenesis of pulmonary arterial hypertension, with evidence of a strong association with M2-like macrophage infiltration." (PMID 27091114, 2016).
rosacea (1 paper, 2025). A chronic erythematous skin disorder that affects the face. "Moreover, GE1111 treatment significantly decreased the gene expression of inflammatory cytokines, including IL-31, MCP-1, and TNF-α in MCs, which are critical in rosacea’s inflammatory response." (PMID 41296102, 2025). "Furthermore, GE1111 reduced the LL-37-induced gene expression of MCP-1, IL-31, and TNF-α in MCs, which upregulated in rosacea." (PMID 41296102, 2025).
spondylitis (1 paper, 2020). The inflammation of a vertebra. "IL-31 is part of the IL-6 family of cytokines and a preliminary study suggests that high baseline IL-31 levels are not only associated with reduced new bone formation based on the modified Stoke Ankylosing Spondylitis Spinal Score (mSASSS) in early SpA, but also with low bone mineral density." (PMID 33273664, 2020).